KL (klotho)
Diseases named in the same sentence as KL in open-access papers (continued):
Sharing a sentence is not in itself a finding about the gene and the disease.
liver cancer (7 papers, 2013 to 2025). An epithelial or non-epithelial malignant neoplasm that arises from the liver. "In the present study, we explored the effects and possible mechanisms relating to Klotho in human liver cancer cell lines, and the clarification of the association and mechanism would contribute to treatment for therapy of liver cancer patients." (PMID 26499380, 2015). "We provide evidence that immunohistochemical Klotho staining is associated with liver cancer progression and poor overall survival, indicating Klotho expression as a poor prognostic marker for survival in HCC patients who underwent surgical resection." (PMID 23516476, 2013). "Klotho was a tumor suppressor gene, and overexpression of Klotho suppressed the proliferation of liver cancer cells partly due to negative regulation of Wnt/β-catenin signaling pathway." (PMID 26499380, 2015). "The results showed that lower expression of Klotho were found in liver cancer cell lines than the immortalized liver cell L02." (PMID 26499380, 2015). "All of the data revealed that Klotho worked as an important antitumor gene in liver cancer progression although some other paper found that high levels of Klotho promoted cancer progression." (PMID 26499380, 2015). "All of the data collectively revealed that Klotho expression inhibited the proliferation of liver cancer cells." (PMID 26499380, 2015). "The MTT assay proved that overexpression or recombinant Klotho administration in liver cancer cells significantly suppressed the proliferation of cancer cells." (PMID 26499380, 2015). "Recently, Klotho is also identified as a tumor suppressor gene in variety of tumors; however, the potential role and the antitumor mechanism remain unclarified in liver cancers." (PMID 26499380, 2015). "In order to clarify the functional relevance of Klotho in liver cancer progression, colony formation assay is performed in liver cancer cells after Klotho expression." (PMID 26499380, 2015). "To explore the Klotho expression of Klotho in liver cancer cell lines, we analyzed Klotho levels in a panel of four liver cancer cell lines by RT-PCR and western blotting analysis." (PMID 26499380, 2015). "As expected, the expression levels of Klotho in three liver cancer cell lines were obviously decreased than those in L02 cells." (PMID 26499380, 2015). "Klotho was a tumor suppressor gene and overexpression of Klotho suppressed the proliferation of liver cancer cells partly due to negative regulation of Wnt/β-catenin signalling pathway." (PMID 26499380, 2015). "Taken together, Klotho expression inhibits the proliferation of liver cancer cells, and Klotho plays an important antitumor role as a potential tumor suppressor." (PMID 26499380, 2015). "The results demonstrated that rKlotho administration inhibited cell growth of liver cancer cells HepG2 and SMMC-7721, and higher expression of Klotho was accompanied with lower proliferation of liver cancer cells." (PMID 26499380, 2015). "Immunohistochemical staining of Klotho levels were statistically analyzed to determine their relationship with clinicopathologic features of the 52 liver cancer patients." (PMID 23516476, 2013). "Then, we further explore the mechanism of Klotho involving in the progression of liver cancers." (PMID 26499380, 2015). "Thus, functional analysis demonstrated that Klotho expression inhibited the proliferation of liver cancer cells and Klotho worked as an important antitumor gene in tumor progression." (PMID 26499380, 2015). "We next evaluated the effect of Klotho on cell proliferation of liver cancer cells." (PMID 26499380, 2015). "It is proved that overexpression or recombinant Klotho administration could inhibit the proliferation of liver cancer cells." (PMID 26499380, 2015). "Also, MTT assay results found that overexpression or recombinant Klotho administration suppressed the proliferation of liver cancer cells HepG2 and SMMC-7721." (PMID 26499380, 2015).
liver cancer (continued). "So, Klotho might be used as a potential target and the study will contribute to treatment for therapy of liver cancer patients." (PMID 26499380, 2015). "However, the relationship and association between the expression of Klotho and primary liver cancers is not clarified till now." (PMID 26499380, 2015). "Thus, Klotho might be used as a potential target, and the study will contribute to treatment for therapy of liver cancer patients." (PMID 26499380, 2015). "Therefore, KL might be a therapeutic target to treat liver cancer patients." (PMID 40004457, 2025). "The liver cancer cell line HepG2 and SMMC-7721 were transfected with p CMV6-Klotho and control plasmid (pCMV6 vector), and the cells were cultured for 10 days." (PMID 26499380, 2015). "All of the data demonstrated that overexpression of Klotho suppressed the proliferation of liver cancer cells and promoted cell apoptosis partly due to negative regulation of Wnt/β-catenin signaling pathway." (PMID 26499380, 2015).
lung adenocarcinoma (7 papers, 2016 to 2025). A carcinoma that arises from the lung and is characterized by the presence of malignant glandular epithelial cells. "KRAS mutations in lung adenocarcinoma were also reported to be associated with co-mutations in STK11/LKB1 (the KL subgroup)." (PMID 29486723, 2018). "Researchers have discovered that the lncRNA SNHG14/hsa-miR-101-3p/KL/PLK1 regulatory axis plays a modulatory role in the immune microenvironment of lung adenocarcinoma." (PMID 41244907, 2025). "In conclusion, this retrospective analysis of the phase III JUNIPER trial identified the KL subtype as a candidate predictive biomarker for abemaciclib efficacy in platinum-refractory KRAS-mutant lung adenocarcinoma." (PMID 40231258, 2025). "Invasive assays and lung tumor-bearing mice models using a human lung adenocarcinoma cell line A549 cells transfected with the Klotho (KL) gene, A549/KL cells, have confirmed that KL suppresses invasive/metastatic potential." (PMID 38267588, 2024). "We established an A549/KL cell line with stable and high Klotho protein expression by transfecting green fluorescent protein (GFP)-klotho plasmids into lung adenocarcinoma A549 cells." (PMID 38267588, 2024). "Interestingly, we found increased expression of γKlotho accompanied with decreased expression of Klotho and βKlotho in several other cancers, including glioblastoma multiforme, lung squamous and lung adenocarcinomas but not in liver hepatocellular carcinoma." (PMID 26556877, 2016).
progeria (7 papers, 2005 to 2023). "The second gene implicated in progeria is KLOTHO encoding a membrane protein of unknown function sharing homology with beta-glucosidases." (PMID 16262891, 2005). "The cellular output parameters were also specified for the Klotho−/− progeria model and compared to standard young C57BL/6 and age-matched Klotho+/+ genotypes." (PMID 35328432, 2022). "Our data do not support the hypothesis that premature CAD is associated with common variants in the progeroid syndrome genes LMNA and KLOTHO." (PMID 16262891, 2005). "Similarly, a decline in gastric ICC has been observed in chronologically aged mice and mice lacking the anti-aging protein α-Klotho (klotho mice, a progeria model)." (PMID 37759758, 2023). "Furthermore, the absence of Klotho in mice accelerates ageing or progeroid syndromes and dramatically shortens the lifespan." (PMID 33438362, 2021).
prostate carcinoma (7 papers, 2017 to 2025). A carcinoma that arises from epithelial cells of the prostate gland. "One study has shown that the C1548T polymorphism of Klotho (KL) gene was associated with prostate cancer." (PMID 35841322, 2023). "A KL single-nucleotide polymorphism (rs3752472) is associated with the risk of prostate cancer (odds ratio = 1.85)." (PMID 33520985, 2020). "Thus, we investigated whether the expression of the anti-aging gene KLOTHO was associated with epigenetic changes in prostate cancer cell lines." (PMID 30460073, 2017). "Methylation in the KL CpG island region KL-M3, including −593 to −406 bp, accounts for the down-regulation of KL mRNA in prostate cancer cell lines DU145 and PC-3." (PMID 33520985, 2020). "FGF23 expression is enhanced in patients with castration-resistant prostate cancer, as well as FGF23/FGFR1/KL in different prostate cancer cell lines." (PMID 33520985, 2020). "The results suggested a remarkable inverse relationship between KLOTHO expression and promoter methylation in prostate cancer cell lines." (PMID 30460073, 2017). "This is the first study demonstrating that the anti-aging gene KLOTHO is expressed in prostate cancer cell lines." (PMID 30460073, 2017). "In prostate cancer, Klotho may act as an endocrine growth factor, facilitating the progression of the disease." (PMID 40004457, 2025). "There are few studies on the relationship between Klotho and prostate cancer." (PMID 35841322, 2023). "Taken together, these results suggest that the immuno-expression patterns of Klotho proteins on prostate cancer tissues may be a valuable tool for tailoring treatment regimens for specific patients." (PMID 37958253, 2023). "The same region is unmethylated in 22Rv1 prostate cancer cells exhibiting KL mRNA expression." (PMID 33520985, 2020). "The most studied is the FGFR-Klotho axis, and Klotho could act as cofactor of endocrine FGFs to bind and induce the activation of FGFRs in breast, pancreatic, and prostate cancers." (PMID 28153033, 2017). "Therefore, this study investigated whether the KLOTHO gene is expressed in 22Rv1, DU145, and PC-3, which are human prostate cancer cell lines, and tried to clarify the epigenetic mechanism that regulates gene expression." (PMID 30460073, 2017).
COVID-19 (6 papers, 2021 to 2024). A disease caused by infection with severe acute respiratory syndrome coronavirus 2. "In this study, we investigated the pathogenic role of Klotho deficiency in COVID-19-associated AKI and explored the therapeutic potential of Klotho-derived peptide 1 (KP1)." (PMID 38239193, 2023). "From a clinical point of view, low serum levels of Klotho are strongly correlated with the same health conditions that have proven to be risk factors for severity of COVID-19, especially type 2 diabetes mellitus, cancer, and chronic kidney disease." (PMID 38133288, 2023). "Low serum levels of Klotho, an anti-aging protein, strongly correlate with the pathogenesis of the same risk factors and manifestations of conditions similar to those expressed in severe COVID-19 cases." (PMID 38133288, 2023). "Whether Klotho deficiency plays a role in the pathogenesis of AKI in COVID-19 patients, however, is unknown." (PMID 38239193, 2023). "We have identified Klotho, a protein that regulates mammalian aging, as a common factor that appears to play a central role in health conditions that predispose patients to severe COVID-19 outcomes as well as in health complications similar to those developed in this disease." (PMID 38133288, 2023). "In the context of COVID-19, Klotho has been shown to have a protective effect on the kidneys of mice infected with SARS-COV2." (PMID 39861814, 2024). "Klotho concentration was found to be significantly elevated in urine samples from the COVID-19-positive participant group compared to the control group." (PMID 39861814, 2024). "There was a greater amount of uEVs in the COVID-19 group and klotho protein was found to be enriched in uEVs from the COVID-19 group." (PMID 39861814, 2024). "The concentration of C-reactive protein, transmembrane serine protease 2, and klotho protein were significantly greater in the urine of COVID-19-positive participants." (PMID 39861814, 2024). "The experimental evidence demonstrates a statistically significant health benefit from Klotho supplementation in a COVID-19 animal model and strongly suggests that Klotho plays an important role in the disease pathogenesis induced by SARS-CoV-2 infection." (PMID 38133288, 2023). "The current manuscript presents original research on the effects of the exogenous application of Klotho, an anti-aging protein, in COVID-19 model mice." (PMID 38133288, 2023). "Klotho levels drop precipitously with AKI, a condition associated with the worst prognosis for COVID-19." (PMID 38133288, 2023). "In this study, mouse models of COVID-19 were used to evaluate the potential survival benefit conferred by Klotho supplementation in mice exposed to SARS-CoV-2." (PMID 38133288, 2023). "This preclinical study should be followed by studies evaluating Klotho levels in COVID-19 patients with varying classifications of disease severity." (PMID 38133288, 2023). "Klotho supplementation was able to significantly increase survival in two independent studies of COVID-19 mice models after exposure to SARS-CoV-2." (PMID 38133288, 2023). "In summary, we have shown in this study that Klotho deficiency, a common feature shared by aging and various preexisting medical conditions, is a key determinant of developing AKI in COVID-19 patients." (PMID 38239193, 2023). "We submit the premise that Klotho plays a central role in COVID-19 pathogenesis and that its acute deficit sharply increases the risk of case severity." (PMID 38133288, 2023). "Klotho is a promising candidate for predicting health status and as a biomarker for evaluating rehabilitation progress post-COVID-19." (PMID 34564326, 2021). "Therefore, we measured the concentration of Klotho in the urine of COVID-19-negative participants and COVID-19-positive participants." (PMID 39861814, 2024).
COVID-19 (continued). "Compared to uEVs isolated from the COVID-19-negative group and the COVID-19-positive mild-to-moderate severity group, Klotho protein enrichment was greater in the COVID-19-positive severe group where densitometric analysis was performed and Annexin A2 was used to assess lane loading." (PMID 39861814, 2024). "At this stage, how exactly Klotho protects kidney from developing AKI in COVID-19 patients remains unknown, but it could be related to its ability to regulate several signaling pathways." (PMID 38239193, 2023). "Further research is required to elucidate the mechanistic role Klotho plays in COVID-19 pathogenesis as well as the possible modulation SARS-CoV-2 may have on the biological aging process." (PMID 38133288, 2023). "In addition, parametric Weibull models revealed a statistically significant survival benefit from Klotho supplementation in both male and female COVID-19 model mice, despite the small sample size of the cohorts." (PMID 38133288, 2023). "Interestingly, the coronavirus disease 2019 (COVID-19) Drug and Gene Set Library in Enrichr suggests that klotho is down-regulated by SARS-CoV-2." (PMID 35368424, 2022). "The acute decrease in Klotho in the skeletal muscle may contribute to the increase in S-Klotho seen in studies of humans, which indicate a role of S-Klotho as a health-preserving myokine in the prevention of severe COVID-19." (PMID 34564326, 2021). "As such, KP1, a small peptide recapitulating Klotho function, could be an effective therapeutic for alleviating AKI in COVID-19 patients." (PMID 38239193, 2023). "Although the main inflammatory pathway in COVID-19 has been considered the Janus Kinase pathway (JAK/STAT), whether Klotho has a role in the JAK/STAT signaling pathway requires further research and validation." (PMID 38133288, 2023). "AUROC between severe and non-severe COVID-19 patients using T0 KL-6 concentrations evaluated through AIA360 was 97.4% and the best cut-off value was 398 U/mL with 89% specificity and 97% sensitivity." (PMID 35206372, 2022). "Consequently, muscle-derived Klotho may represent a novel myokine that may help explain some of the health and anti-aging effects of PA via anti-inflammatory, anti-oxidative effects and the preservation of vessel functions, which ultimately protect against severe COVID-19." (PMID 34564326, 2021). "Since we identified increased Klotho protein in the urine of COVID-19-positive participants compared to COVID-19-negative participants, we next investigated whether Klotho protein is enriched in uEVs from the COVID-19 group." (PMID 39861814, 2024).
Duchenne muscular dystrophy (6 papers, 2018 to 2025). Duchenne muscular dystrophy (DMD) is a neuromuscular disease characterized by rapidly progressive muscle weakness and wasting due to degeneration of skeletal, smooth and cardiac muscle. "Prior works showed that transcriptional expression of Klotho in muscles is suppressed transiently after injury, with aging, and after disease onset in Duchenne muscular dystrophy, a muscle wasting disorder." (PMID 40869307, 2025). "Of note, Wehling-Henricks and colleagues described that epigenetic silencing of klotho in muscular dystrophy contributes to the disturbed regeneration and fibrosis in mdx mice, the mouse model for Duchenne muscular dystrophy." (PMID 29973273, 2018). "A study in mdx mice, the mouse model for Duchenne muscular dystrophy (DMD), showed that that epigenetic silencing of Klotho in muscle occurs at the onset of DMD and contributes to the disturbed muscle regeneration and muscle fibrosis observed in mdx mice." (PMID 36188832, 2021).
glomerulonephritis (6 papers, 2012 to 2023). A renal disorder characterized by damage in the glomeruli. "Nonetheless, a very recent paper based on renal biopsies of patients with glomerulonephritis and variable renal damage, for the first time showed reduced tubular TM-Klotho expression associated with reduced serum levels of s-Klotho." (PMID 25873958, 2015). "The transgenic mice were challenged using nephrotoxic serum (NTS)-induced glomerulonephritis to examine the potentially protective effects of systemic or podocyte-derived Klotho on the glomerulus." (PMID 36813870, 2023). "A recent paper with histologic data from patients with glomerulonephritis showed parallel reduction of renal Klotho and of s-Klotho together with increments in FGF23, which is in agreement with our data." (PMID 25873958, 2015). "The transgenic overexpression of Klotho in a mouse model of glomerulonephritis resulted in increased survival, attenuated glomerular and tubulointerstitial changes, and reduced proteinuria and blood urea nitrogen." (PMID 22121479, 2012). "The nephroprotective effects of Klotho have also been tested in an animal model of glomerulonephritis." (PMID 22121479, 2012). "The lack of protection afforded by overexpression of Klotho in podocytes when mice were challenged with NTS-induced glomerulonephritis confirms that locally expressed Klotho is unlikely to have a glomeruloprotective role." (PMID 36813870, 2023). "To test whether increased expression of Klotho in hepatocytes or in podocytes protect against glomerular injury, we induced NTS glomerulonephritis in Alb-hKL and Pod-hKL mice." (PMID 36813870, 2023).